MYC (MYC proto-oncogene, bHLH transcription factor)
Diseases named in the same sentence as MYC in open-access papers (continued):
Sharing a sentence is not in itself a finding about the gene and the disease.
Burkitt lymphoma (continued). "Similarly, the improved pharmacodynamics could be replicated by another BRD4-targeting PROTAC, ARV-825, in Burkitt’s lymphoma cell lines showing promising results for MYC-driven malignancies." (PMID 33324551, 2020). "MYC is deregulated in almost all human cancers, especially Burkitt lymphoma (BL), other aggressive B cell lymphomas (BCLs) and T cell lymphomas (TCLs)." (PMID 33298911, 2020). "Interestingly, early observations indicate that c-MYC-driven Burkitt lymphoma may be particularly dependent on MCL-1, with 7 out of 7 tested cell lines responding to nanomolar concentrations of S63845." (PMID 33308268, 2020). "Burkitt lymphoma (BL) is characterized by a translocation of the MYC oncogene that leads to the upregulation of MYC expression, cell growth and proliferation." (PMID 30779244, 2019). "The epigenetic mode of BIM repression by EBNA3A and EBNA3C may be important for Burkitt’s lymphoma development, since it can create an environment permissive for MYC overexpression, even after EBNA3A and EBNA3C expression is shut down, as the virus progresses through different stages of latency." (PMID 29562595, 2018). "The representative cationic porphyrin TMPyP4, an end stacker binding the major parallel MYC G4, provided early proof of principle that stabilization of G4 structures could silence MYC transcription given its effects in Burkitt’s lymphoma Ramos and CA46 cell lines." (PMID 30597997, 2018). "To determine whether DNMT3B overexpression levels in human B- and T-cell lymphoma cell lines depend on high levels of endogenous MYC, we analyzed a panel of human T-cell lymphoma and Burkitt’s lymphoma cell lines before and upon knock-down of MYC via tetracycline-inducible shRNA." (PMID 29100357, 2017). "The disruption to DNase hypersensitive elements in Burkitt’s lymphoma cells led to the characterization of chromatin modifications and mapping of the DNA elements regulating the endogenous MYC promoter as a means of understanding mechanisms of this MYC-driven cancer." (PMID 28398229, 2017). "To determine whether DNMT1 and DNMT3B transcription in T-ALL and Burkitt’s lymphoma-like cells is directly regulated by oncogenic MYC, we performed chromatin immunoprecipitation (ChIP) analysis measuring MYC binding to the genomic loci of DNMT1, DNMT3A and DNMT3B." (PMID 29100357, 2017). "To determine whether DNMT3B overexpression in T-ALL and Burkitt’s lymphoma cells is MYC-dependent, we took advantage of the tetracycline-regulated c-MYC allele in mouse T-ALL (EμSRα-tTA;tet-o-MYC) as well as in a human Burkitt’s lymphoma-like cell line model (P493-6)." (PMID 29100357, 2017). "In Burkitt lymphoma (BL), c-MYC is translocated to one of the immunoglobulin loci resulting in its constitutive expression." (PMID 22132187, 2011). "The molecular feature of Burkitt lymphoma (BL) is the translocation that places MYC under the control of immunoglobulin gene regulatory elements." (PMID 20930934, 2010). "A paradigm for c-Myc deregulation is offered by Burkitt Lymphoma (BL), where chromosomal translocations that join MYC with immunoglobulin (Ig) heavy- (Igh) or light-chain (Igκ, Igλ) loci are the crucial initiating oncogenic events." (PMID 20930934, 2010). "Inula viscosa extract supresses cell cycle and proliferation genes (c-MYC, CCND1) while inhibiting anti-apoptotic genes (BCL2, BCL2L1, BCL11 A), demonstrating significant anticancer effects on Burkitt’s lymphoma (BL) cells." (PMID 40214725, 2025). "This is based on molecular studies showing similarity to DLBCL rather than Burkitt lymphoma (BL), for example, lacks MYC-rearrangement but harbours an 11q gain/loss pattern." (PMID 40949653, 2024). "In the last WHO revision of the classification of tumors of hematopoietic and lymphoid tissues, there is a subtype with MYC rearrangement distinct from other B-ALL types and Burkitt lymphoma (ref OMS 2022)." (PMID 39594704, 2024).
Burkitt lymphoma (continued). "Given the pivotal role of MYC in EBV-driven B-cell proliferation and Burkitt’s lymphoma, its expression following treatment with TERT inhibition was analysed in more detail." (PMID 37345011, 2023). "For example, translocation of MYC and the heavy chain loci of immunoglobulins (IGH) was observed in about 85% of Burkitt lymphomas." (PMID 37443779, 2023). "When these facts are combined, it is evident that Burkitt’s lymphoma phenotype resulted from an activated PI3K and MYC combination." (PMID 36986499, 2023). "Our results show strong potential of the drug combination for treatment of Burkitt lymphoma and DLBCL, even in a MYC-independent manner." (PMID 36792656, 2023). "For example, in Burkitt’s lymphoma cells, high concentrations and continuous exposure to BRD4 inhibitors were required to suppress the expression of c-MYC." (PMID 36733715, 2023). "In GCB DLBCL, PTEN deletions and amplification of the microRNA-17-92 cluster (MIR17HG) sustain cell proliferation, while similar deregulations are also in place in Burkitt lymphoma (BL) cells, in which the constitute activation of the MYC oncogene directly activates the PI3K/Akt/mTOR pathway." (PMID 37762410, 2023). "JQ-1 or I-BET treatment leads to the transcriptional suppression of MYC target genes, resulting in antitumor effects in MYC-driven models of AML, Burkitt’s lymphoma and multiple myeloma." (PMID 34050894, 2022). "Burkitt lymphoma (BL) is a highly aggressive non-Hodgkin lymphoma and of which Epstein-Barr virus (EBV) and constitutive expression of c-MYC protein play an important role in the development." (PMID 35193582, 2022). "Among hematologic malignancies, BCL-W is highly expressed in a subset of c-MYC-expressing DLBCL and Burkitt lymphomas as well as B-CLL cells, although it appears dispensable for their survival." (PMID 34576319, 2021). "Here we interrogate how one MYC co-factor, host cell factor (HCF)–1, contributes to MYC activity in a human Burkitt lymphoma setting." (PMID 33416496, 2021). "In addition to oncogenic MYC translocations, Burkitt lymphoma (BL) depends on the germinal centre (GC) dark zone (DZ) B cell survival and proliferation programme, which is characterized by relatively low PI3K-AKT activity." (PMID 31719683, 2020). "Preclinical data are illustrated by Burkitt lymphoma (BL; a rare subtype of NHL with a specific morphology and characterized by MYC translocation in 95–99% of the cases) models." (PMID 33092116, 2020). "MYC is often overexpressed and/or dysregulated in cancer, including mouse PCT, as well as human myeloma and Burkitt’s lymphoma." (PMID 32923678, 2020). "It was reported that combining constitutive c-MYC expression and PI3K activity in germinal center B cells of the mouse led to Burkitt lymphoma-like tumors." (PMID 32695674, 2020). "Myc proto-oncogene, known to be the major regulator and driver of Burkitt’s lymphoma, we wanted to assess the effect of PMA stimulation on expression of MYC (both wild type and translocated)." (PMID 32788680, 2020). "In these cases, independently of the immunophenotype exhibited by tumor cells, MYC, BCL2, and BCL6 rearrangements should be investigated for the differential diagnosis among HGBL DH/TH, HGBL NOS, and Burkitt lymphoma." (PMID 31388760, 2019). "Burkitt lymphoma (BL) is a highly aggressive B‐cell non‐Hodgkin lymphoma (NHL) characterized by the translocation and deregulation of the MYC gene on chromosome 8." (PMID 30706675, 2019). "Anti-tumor activity and repression of MYC by BET inhibitors have been shown in various malignancies including multiple myeloma (MM), Burkitt’s lymphoma, and acute myelogenous leukemia (AML)." (PMID 30018745, 2018). "Here, we provide evidence that in Burkitt lymphoma the MYC oncogene is a client protein of HSP90, and that MYC expression can be targeted by inhibiting HSP90 function with readily available pharmacologic inhibitors." (PMID 30453475, 2018).
Burkitt lymphoma (continued). "Together, we demonstrate that the MYC oncogene and its network can be targeted indirectly through the use of HSP90 inhibitors in Burkitt lymphoma." (PMID 30453475, 2018). "Using co-immunoprecipitation, we furthermore demonstrated a direct interaction between MYC and HSP90, indicating that MYC is an HSP90 client protein in Burkitt lymphoma." (PMID 30453475, 2018). "Silencing LAT1 inhibits the proliferation of Burkitt’s lymphoma cells (Daudi) and neuroblastoma cells (BE-2C), indicating that LAT1 induction by MYC is tied with cancer cell proliferation." (PMID 30103560, 2018). "In combination with the promoter binding assay, the expression analysis provides evidence for a direct transcriptional of regulation DNMT3B by MYC in human T-ALL and Burkitt’s lymphoma." (PMID 29100357, 2017). "Based on our expression profiling, we conclude that DNMT1 and DNMT3B are consistently overexpressed in MYC-driven T-ALL and Burkitt’s lymphoma cell lines, while DNMT3A is overexpressed in human T-ALL cell lines only." (PMID 29100357, 2017). "Subsequent ChIP analysis revealed that MYC occupies sites within the DNMT1 and DNMT3B regulatory regions, suggesting a direct transcriptional regulation in mouse T-ALL and human Burkitt’s lymphoma-like cells." (PMID 29100357, 2017). "Taken together, DNMT1 and DNMT3B expression exhibited a correlation to MYC levels in both mouse T-ALL and human Burkitt’s lymphoma models." (PMID 29100357, 2017). "In both T-ALL and Burkitt’s lymphoma-like cells, treatment with 20ng/mL DOX for 1 and 2 days quickly abrogated MYC transcription; DNMT3B showed a decrease of mRNA followed by the corresponding protein." (PMID 29100357, 2017). "In summary, the genomic location analysis together with expression profiling indicates that MYC directly binds to DNMT1 and DNMT3B in T-ALL and Burkitt’s lymphoma, thereby establishing both DNMTs as direct transcriptional targets of the MYC oncoprotein." (PMID 29100357, 2017). "MYC rearrangement, typically detected by fluorescence in situ hybridization (FISH), is characteristic for Burkitt lymphoma." (PMID 29250206, 2017). "We identified canonical E-box sequences in close proximity to the MYC enrichment peak near the transcription start site (TSS) of DNMT1 and DNMT3B in both T-ALL, and Burkitt’s lymphoma-like cells." (PMID 29100357, 2017). "Knock-down of endogenous MYC in human T-ALL and Burkitt’s lymphoma cell lines supports above findings, indicating that DNMT3B overexpression directly depends on high levels of MYC." (PMID 29100357, 2017). "By obtaining MYC translocation in addition to BCL2 rearrangement, these cells transform to cells that morphologically and phenotypically resemble Burkitt lymphoma or DLBCL, and these patients invariably have a poor prognosis." (PMID 28375188, 2017). "In human Burkitt’s lymphoma, mouse plasmocytoma, and rat immunocytoma, activation of the c-MYC gene is brought about by chromosomal translocation of c-MYC into one of the three immunoglobulin heavy or light chain loci." (PMID 24130880, 2013). "To ensure precision in the automated staining protocol, we stained identical samples of tonsil, Burkitt lymphoma, and 22 DLBCL cases including the primary DLBCL case #9 (DLBCL with MYC-translocation near the cut-point for MYC IHC-High) three times." (PMID 22511926, 2012). "The acquisition of MYC translocation is reported in DLCL, lymphoblastic lymphoma and pre-B acute lymphoblastic leukemia transformation from FL, but only rarely in atypical Burkitt's lymphoma or Burkitt's leukemia transformation." (PMID 21736761, 2011). "In this case, MYC was positive (approximately 80%), and fluorescence in situ hybridization (FISH) confirmed IG rearrangements, aligning with the genetic characteristics of Burkitt’s lymphoma and further substantiating the diagnosis." (PMID 41561748, 2025).
Burkitt lymphoma (continued). "In Burkitt lymphoma (BL) and other types of non-Hodgkin lymphomas (NHL) originating from germinal centers, decreased expression of miR-28 was found, resulting from negative regulation of this miRNA by the MYC oncogene." (PMID 40563399, 2025). "To investigate whether c-MYC was necessary for the WS6-mediated cytotoxicity, we used the P493-6 Burkitt lymphoma cell line, which expresses a doxycycline-repressible c-MYC transgene." (PMID 41002386, 2025). "EBV in Burkitt’s lymphoma provides a survival advantage to proliferating cells due to c-MYC translocation rather than directly driving proliferation throughout." (PMID 39772235, 2024). "Our findings also indicate that H-DNA-forming sequences (from a translocation breakpoint hotspot in the c-MYC gene in Burkitt lymphoma) confer inherent mutagenic properties regardless of the tissue type." (PMID 39043652, 2024). "Interestingly, c-MYC was reported to transactivate LDHA promoter in c-MYC-transformed human lymphoblastoid cells and Burkitt lymphoma cells." (PMID 37791390, 2024). "Moreover, MYC abundance represses EBV reactivation and controls the lytic switch in Burkitt lymphoma." (PMID 39599775, 2024). "MYC, located on chromosome 8q24.21, is overexpressed in up to 45% of solid tumors and translocated in up to 15% of diffuse large B-cell lymphomas (DLBCL) and multiple myeloma (MM) patients, and in 95–100% of all Burkitt lymphoma (BL) patients." (PMID 39596160, 2024). "Likewise, global downregulation of MYC target genes has been observed after treatment with decitabine in T-ALL, AML and Burkitt lymphoma." (PMID 36765607, 2023). "It has a Burkitt-like immunophenotype (CD10+, BCL6+, BCL2−) but MYC expression is weak or negative, lacks MYC rearrangement, and is in contrast to Burkitt lymphoma 50% of the cases express LMO2." (PMID 37555980, 2023). "DNA G4 was first found to be involved in gene regulation by Hurley and coworkers, who observed that treatment of Burkitt’s lymphoma cells with G4 ligands, e.g. PDS and TMPyP4, led to diminished transcription of MYC gene, whose promoter contains G4-forming sequence." (PMID 37427784, 2023). "In addition, overexpressed enzymes like PHGDH and PSAT1 promote the MYC/miR-494/enhancer of zeste homolog 2 (EZH2) feed-forward loop and are at least partially driven by MYC/ATF4 signaling in Burkitt lymphoma cells to sustain metabolic reprogramming." (PMID 36582785, 2022). "The MYC and CD38 status with epidemiological data in 108 patients with suspected Burkitt lymphoma." (PMID 35167621, 2022). "To evaluate this, we performed EZH2 depletion in representative MYC(N)-driven small cell carcinoma NCI-H526 and NCI-H82 cells as well as MYC-driven Burkitt’s lymphoma Daudi cells, which are characterized by MYC(N) overexpression due to chromosome amplification or translocation." (PMID 35013218, 2022). "Cytogenetics revealed the absence of an MYC rearrangement involving chromosomes 2, 14, or 22, normally found in Burkitt lymphoma, or the classic telomeric losses and proximal gains observed in BLL." (PMID 36158446, 2022). "Suppression of the AL928768.3 eRNA expression allowed selective downregulation of MYC gene expression and the inhibition of cell growth in Burkitt lymphoma cells, but not in B cells without IGH/MYC abnormality." (PMID 35563017, 2022). "The Burkitt’s lymphoma cell line Ramos, which is also characterized by MYC translocation and expression of Mcl‐1 but not BCL2, showed a similar sensitivity profile." (PMID 34632715, 2022). "Burkitt lymphoma (BL) is a highly aggressive B- NHL, which is characterized by the translocation and dysregulation of the MYC gene on chromosome 8 and may involve multiple organ systems." (PMID 33985517, 2021). "As expected, mutations in frequent drivers such as CREBBP, KMT2D,TNFRSF14 and RRAGC were more frequent among follicular lymphomas, those of MYC, CCND3 and ID3 prevailed among Burkitt lymphoma and those of BTG2, PIM1, SGK1 and SOCS1 were more frequent among DLBCL." (PMID 33945543, 2021).
Burkitt lymphoma (continued). "In Burkitt lymphoma, which is characterized by high MYC expression, two circRNAs, ZDHHC11 and ZDNN11B, containing multiple binding sites for miR-150 were upregulated following upregulation of the MYC that targets MYB." (PMID 34502399, 2021). "DPY30 was found to be upregulated in Burkitt’s lymphoma, and its downregulation can have a negative effect on cell transformation dependent on MYC activity." (PMID 33302406, 2020). "Studies on Burkitt’s lymphoma have shown that DPY30, like other KMT2 core subunits, is upregulated by the MYC oncoprotein and is significant for the binding of MYC to its target genes; thus, it plays an important role in MYC-driven tumorigenesis." (PMID 33302406, 2020). "MYC cooperates and enhances PI3K signaling in Burkitt lymphoma through multiple modes." (PMID 31645904, 2019). "Together, this indicates that HSP90 inhibition affects transcription and protein stability of MYC similar to Burkitt lymphoma, even if the c-myc gene is not translocated." (PMID 30453475, 2018). "We treated Burkitt lymphoma cell line (Raji) with 1 μM 17-DMAG for three days and found decreased enrichment of active chromatin marks, H3K4me3, compared to untreated control at the translocated MYC locus region." (PMID 30453475, 2018). "Western blot analysis of LAT1 null Burkitt’s lymphoma cells and neuroblastoma cells identified a reduction in MYC protein; however, the levels of MYC mRNA were not reduced." (PMID 30103560, 2018). "Our results indicate that HSP90 inhibition affects transcription and protein stability of MYC similar to Burkitt lymphoma, even if the c-myc gene is not translocated like in CML." (PMID 30453475, 2018). "By utilizing a tetracycline-regulated MYC transgene in a mouse T-ALL (EμSRα-tTA;tet-o-MYC) and human Burkitt’s lymphoma (P493-6) model, we demonstrated that DNMT1 and DNMT3B expression depend on high MYC levels, and that their transcription decreased upon MYC-inactivation." (PMID 29100357, 2017). "To determine whether MYC and DNMT expression correlate in a time dependent manner, we treated mouse T-ALL (2833) and human Burkitt’s lymphoma-like cells (P493-6) for 1 and 2 days with 20 ng/mL DOX." (PMID 29100357, 2017). "Hence, our finding that MYC directly increases transcription of DNMT3B in T-ALL and Burkitt’s lymphoma reveals a novel mechanism of deregulation in cancer." (PMID 29100357, 2017). "Hence, shRNA-mediated knock-down of endogenous MYC in human T-ALL and Burkitt’s lymphoma cell lines downregulated DNMT3B expression." (PMID 29100357, 2017). "Interestingly, decitabine was able to suppress Eμ-driven translocated MYC through upregulation of NF-ĸB and ID2 and thereby inhibit cell proliferation in Burkitt’s lymphoma." (PMID 28505071, 2017). "In a recently employed approach, MYC expression is blocked by impairing a BET bromodomain protein, a strategy that has proved effective both in vitro and in xenograft models in a range of hematological neoplasms, including Burkitt lymphoma." (PMID 26910115, 2016). "Burkitt lymphoma (BL) is the first human cancer to be associated with the Epstein-Barr virus (EBV), the first tumor to exhibit a chromosomal translocation activating an oncogene (MYC), and the first lymphoma to be associated with human immunodeficiency virus (HIV) infection." (PMID 26468873, 2015). "Collectively, our results showed that MYC translocation-positive and MYC translocation-negative Burkitt lymphoma cases are slightly different in terms of microRNA and gene expression." (PMID 26453442, 2015). "We studied the microRNA profile of MYC translocation-positive and MYC translocation-negative Burkitt lymphoma cases in order to uncover possible differences at the molecular level." (PMID 26453442, 2015).